ATG12P1 (autophagy related 12 pseudogene 1)
Synonyms: formerly ATG12P
Gene: Processed pseudogene on chromosome 17 (73,067,870 to 73,068,288, reverse strand). Ensembl gene ENSG00000266501.
Diseases named in the same sentence as ATG12P1 in open-access papers:
ATG12P1 is named in the same sentence as 1 disease in open-access papers, as found by Europe PMC text mining. Sharing a sentence is not in itself a finding about the gene and the disease.
ATG12P1 shares sentences with these, for which no sentence is quoted: breast tumors (1 paper).